MYC (MYC proto-oncogene, bHLH transcription factor)
Diseases named in the same sentence as MYC in open-access papers (continued):
Sharing a sentence is not in itself a finding about the gene and the disease.
osteosarcoma (continued). "Previous study demonstrated that prometastasis genes such as MYC 7, 8 and RAS 9 facilitate osteosarcoma metastasis and metastasis‐resistant genes including nm23 10, p16 11 and KiSS‐1 metastasis‐suppressor 12 inhibited the metastasis process in osteosarcoma." (PMID 30868060, 2019). "Interestingly, these authors identified that MYC is a direct target of RUNX2, and they also demonstrated that MYC is required for the survival of osteosarcoma cells." (PMID 30463392, 2018). "Together, our study demonstrated that DGKZ might act as an oncogene in osteosarcoma via its possible interaction with ERK1/2 and MYC pathway." (PMID 30662872, 2018). "We first compared the expression of MYC in two osteosarcoma cell lines (U2OS and 143B) and a control human fibroblast cell line (BJ), our result uncovered that MYC expression is up-regulated in osteosarcoma cells compared to the control fibroblasts." (PMID 29644114, 2018). "Intriguingly, inactivation followed by the reactivation of MYC in a conditional osteosarcoma mouse model does not reverse the entire gene expression program controlled by MYC." (PMID 28505071, 2017). "Expression analysis might give further insights whether c-MYC, MYCN, and/or other oncogenes orchestrate together in H3F3A G34 mutant osteosarcomas." (PMID 28484590, 2017). "Additionally, high-IMP_Risk patients displayed genetic amplifications in oncogenes, including MYC and MCL1, that might be potential therapeutic targets for osteosarcoma treatment." (PMID 39359731, 2024). "Moreover, this difference in survival is not driven by MYC-overexpression, suggesting a novel mechanism for some aggressive osteosarcomas." (PMID 38562379, 2024). "Moreover, many MYC bound super enhancer genesincluding CDK6, TGFB and CALM2 are downregulated upon THZ1 treatment, further confirming that role of THZ1 in targeting super enhancer signaling in osteosarcoma." (PMID 29644114, 2018). "Whether regulation of DGKZ on downstream MYC pathway in osteosarcoma is through a direct or indirect route is still not clear." (PMID 30662872, 2018). "The gain of 8q might confer a tumor propagating gene dosage effect, although c-MYC is not amplified in the six H3F3A mutant osteosarcomas presented here." (PMID 28484590, 2017). "However, c-MYC amplification, 6p12–21 amplification or chromothripsis, both hallmark copy number alterations in osteosarcomas, were absent in all six H3F3A mutant osteosarcomas." (PMID 28484590, 2017). "These therapies include indirectly targeting MYC in combination with the PI3K pathway, mechanistic target of rapamycin (mTOR), or histone deacetylases (HDACs) for the treatment of T-cell acute lymphoblastic leukemia, pancreatic ductal adenocarcinoma, and osteosarcoma, respectively." (PMID 27081479, 2016). "For unknown reasons, we could not confirm the frequent overexpression of MYC, as noted in our osteosarcoma set, in the validation set." (PMID 25551557, 2014). "MYC gene amplification was assessed by Southern blot analysis using frozen tissue samples in five cases of pagetic osteosarcoma and 53 cases of primary (non-pagetic) osteosarcoma." (PMID 18521214, 1997). "However, the entire MYC target gene set signature in osteosarcoma prognosis has not been reported." (PMID 37342196, 2023). "Although there were no available antibodies to TAC4, the protein expression of MYC, P4HA1, and RAMP1 was found to be significantly higher in osteosarcoma tissues than in normal tissues." (PMID 37055822, 2023). "Therefore, new therapeutic approaches are needed to improve therapeutic efficacy in osteosarcoma patients, and we hypothesize that the FAM83H might be involved in the oncogenesis of the osteosarcoma based on the role of FAM83H in cancer progression in conjunction with MYC and the β-catenin pathway." (PMID 31215499, 2019).
bladder cancer (188 papers, 2006 to 2026). "Analysis of human bladder cancer specimens reveals that HK2 expression positively correlates with MYC and LDHA levels and associates with worse patient survival, particularly in patients with hyperglycemia." (PMID 41951587, 2026). "In bladder cancer, the high expression of MYC was associated with metastasis related genes that takes role in apical junction (p = 0.002) and MYC signaling pathway genes (p = 0.008)." (PMID 33723286, 2021). "Corresponded to the detected abnormal m6A modification of MYC mRNA in many cancers, including myeloid leukemia 15, bladder cancer 16, and GBM 29, aberrant MYC expression was also caused by METTL3-mediated m6A modification in PCa." (PMID 32284755, 2020). "On the one hand, tumors harboring ESC-like gene expression signature with active targets of SOX2, OCT4, and MYC were associated with poor pathological differentiation and poor prognosis in brain, breast, and bladder cancer patients." (PMID 32427884, 2020). "Although signaling elicited by the stem cell factors SOX2, OCT4, KLF4, and MYC has been associated with cancer progression in several tumors, it has remained unclear how these signaling molecules mediate bladder cancer progression." (PMID 32427884, 2020). "We investigated the signals downstream from FGFR3 responsible for the observed higher levels of MYC mRNA and greater MYC protein stability in bladder cancer cells harboring FGFR3 mutations." (PMID 29463565, 2018). "An expression QTL for MYC has been described for the bladder cancer risk locus in histologically normal bladder samples from Chinese subjects, albeit from a very small set, but not in adipose or blood tissue samples from European subjects." (PMID 27579533, 2016). "The bladder cancer susceptibility variant rs9642880 (G/T) is located 30 kb upstream of the MYC gene and is in weak LD with the other risk variants on the 8q24." (PMID 23752272, 2013). "Rs9642889, 30 kb upstream of the MYC gene on chromosome 8q24.21, confers susceptibility to bladder cancer and influences expression of MYC." (PMID 23284801, 2012). "c-MYC mRNA methylation has been linked to poor prognosis in bladder cancer patients." (PMID 40747118, 2025). "With respect to copy number gains and amplifications in bladder cancer patients, alterations of the c-MYC gene, including copy number gains and amplifications, are linked to genetically unstable bladder cancers characterized by a high histologic grade and/or invasive growth." (PMID 28881578, 2017). "Genome-wide association studies of bladder cancer identified single-nucleotide polymorphisms (SNPs) on chromosome 8q24, upstream of the MYC oncogene, on chromosome 3q28 near the TP63 tumor suppressor gene, and in the PSCA gene to be associated with bladder cancer risk." (PMID 25234557, 2014). "Interestingly, several bladder cancer risk variants including MYC and FGFR3/TACC3 show stronger association with low risk tumors, confirming the heterogeneous nature of bladder cancer." (PMID 23752272, 2013). "Furthermore, an exonic circular RNA (circNR3C1) which is generated from NR3C1 gene, interacts with bromodomain-containing protein 4 (BRD4) causing dissociation of BRD4/MYC complex and preventing MYC function as a transcription factor to inhibit bladder cancer progression." (PMID 39031286, 2024). "Here we identify a noncanonical, nuclear role of hexokinase 2 (HK2) that couples systemic hyperglycemia to MYC-driven glycolysis and stemness in bladder cancer." (PMID 41951587, 2026). "The PI3K signaling pathway has been established as a therapeutic target in bladder cancer and pathways such as MYC, WNT, TGF-β, and PI3K have been shown to play critical roles in bladder cancer progression." (PMID 40589759, 2025). "Bladder cancer employs a multilayer PTM network to cooperatively maintain the stability of oncogenic MYC, driving tumor progression." (PMID 41303712, 2025).
bladder cancer (continued). "POLD1 also frequently co-occurs with oncogenic drivers like APC, BRCA2, and MYC, notably in colorectal and bladder cancers." (PMID 40661943, 2025). "Bladder cancer employs a multilayer PTM network to cooperatively maintain the stability of oncogenic MYC." (PMID 41303712, 2025). "In bladder cancer (BC), MYC serves as a novel substrate of SETD8 to be methylated at lysine 412, which enhances MYC protein stability by preventing the CHIP‐mediated degradation and ultimately promotes tumor growth." (PMID 40091385, 2025). "For example, the METTL3-AFF4-SOX2/MYC novel signaling axis was shown to promote self-renewal and tumor heterogeneity in bladder cancer stem cells (BCSCs), demonstrating the importance of m6A modifications." (PMID 38355684, 2024). "Our findings revealed that YARS1 interacts with the well‐known oncogene MYC, and together they play crucial roles in regulating ferroptosis, senescence and stemness in bladder cancer cells." (PMID 38506098, 2024). "Further, MYC activation overrides GClnc1 inhibition, restoring cell invasiveness, while GClnc1 up-regulation activates MYC, resulting in bladder cancer progression." (PMID 37450923, 2024). "For instance, FGFR3 activation leads to MYC expression by enhancing the MAPK pathway in bladder cancer." (PMID 39482742, 2024). "Studies in FGFR3 dependent bladder cancer cells have also showed the key role of MYC in mediating growth inhibition due to FGFR blockade." (PMID 39031286, 2024). "All the results suggested that USP1 is an oncogene in bladder cancer, which promotes cancer progression by targeting c-MYC." (PMID 39513905, 2024). "For instance, METTL3 is highly expressed and promotes bladder cancer by promoting the expressions of MYC and AFF4; inhibition of METTL3 reduces bladder tumor cell proliferation, migration, and invasion." (PMID 39457524, 2024). "The clinical relevance of KLF16 and MYC in bladder cancer was evaluated through analyses of public databases and immunohistochemistry." (PMID 39551759, 2024). "In conclusion, our study suggests that YARS1 modulates ferroptosis, senescence and stemness in bladder cancer cells by interacting with MYC." (PMID 38506098, 2024). "Next, we explored the mechanisms and found that USP1 bound to and stabilized c-MYC by mediating its deubiquitination, thereby promoting the progression of bladder cancer." (PMID 39513905, 2024). "Among these genes, MYC was found to interact with YARS1 in bladder cancer and to regulate cellular senescence and ferroptosis." (PMID 38506098, 2024). "Wu has recently reported that BRD4 can positively regulate EZH2 gene expression through upregulation of c-MYC and that the BRD4/c-MYC/EZH2 axis plays a vital role in the regulation of bladder cancer progression." (PMID 36733715, 2023). "For instance, circPTPRA suppressed bladder cancer growth and metastasis via downregulation of m6A-modified MYC proto-oncogene, bHLH transcription factor (MYC) and fascin actin-bundling protein 1 (FSCN1) through interacting with IGF2BP1." (PMID 37370759, 2023). "Through m6A, METTL3 can either directly upregulate MYC expression or enhance the expression of AFF4, the transcription promoter of MYC, to regulate the expression of MYC in bladder cancer." (PMID 37996892, 2023). "METTL3 can induce m6A modification of MYC mRNA and consequently increases its expression in bladder cancer." (PMID 35761379, 2022). "For example, in bladder cancer, the m6A regulator METTL3 promotes the progression of bladder cancer through the AFF4/NF-kB/MYC signaling network." (PMID 33952279, 2021). "LncRNA GClnc1 promoted the proliferation and invasion of bladder cancer tissues by activating MYC proto-oncogene." (PMID 34714841, 2021).
bladder cancer (continued). "As we expected, engineered CRISPR/Cas13d inhibited the mRNA and protein levels of MYC, and thus suppressed cell proliferation, migration, invasion and induced apoptosis of bladder cancer cells in vitro." (PMID 33816560, 2021). "Suppression of the expression of these circRNAs reduces the proliferation and migration of tumor cells A circRNA, circ_0068307, was also found to stimulate MYC gene expression and bladder cancer cell proliferation by binding miR-147." (PMID 34440124, 2021). "A recent study found that overexpression of m6A methyltransferase METTL3 facilitates tumor development through AFF4/NF-κB/MYC signal pathway in bladder cancer." (PMID 34367534, 2021). "The MYC mRNA expression levels were decreased significantly between NC aptazyme and hTERT aptazyme group in bladder cancer 5637 and T24 cells." (PMID 33816560, 2021). "It has been reported that thymoquinone can inhibit the expression of MYC gene and then suppress invasion and metastasis in bladder cancer cells." (PMID 34692520, 2021). "The ectopic expression of METTL3 potentiates bladder cancer progression through the AFF4/NF‐κB/MYC network." (PMID 33029866, 2020). "METTL3 promoted the proliferation and metastasis of bladder cancer via the AFF4/NF‐κB/MYC signalling network in an m6A‐dependent manner." (PMID 32808488, 2020). "To determine the metabolic stress resulted from Vitamin K2-elevated glycolysis in bladder cancer cells, we assessed the NADH:NAD+ ratio, cyclic AMP content and c-MYC expression whose alteration are susceptible to glucose starvation." (PMID 32382009, 2020). "The PCR signals of six genes (KLK3, TMPRSS2, KLK4, IGF1R, VEGF, and MYC) were successfully amplified in bladder cancer cell lines." (PMID 32781788, 2020). "An existing study further demonstrated that METTL3 promotes the expression of MYC in bladder cancer cells by augmenting the m6A modification of MYC mRNA, which was consistent with our findings." (PMID 33048840, 2020). "METTL3 has been reported to promote the bladder cancer progression by AFF4/NF-κB/MYC signaling pathway where it upregulates the oncoprotein MYC expression in both direct and indirect manner." (PMID 32194861, 2020). "They found that ERH gene knockdown suppressed MYC-mediated migration and invasion in bladder cancer T24 cells." (PMID 33552118, 2020). "The AFF4/NF-κB/MYC (AF4/FMR2 Family Member 4/ Nuclear Factor Kappa B/ Myelocytomatosis oncogene) signaling network plays a vital role in the upregulation of METTL3 in bladder cancer." (PMID 32765970, 2020). "As a main component in the so-called m6A ‘writer’, METTL3 was reported to have the ability to promote bladder cancer progression via AFF4/NF-κB/MYC signaling network by an m6A dependent manner." (PMID 31228940, 2019). "Disruption of this FGFR3/MYC loop in bladder cancer cell lines by treatment with FGFR3, p38, AKT, or BET bromodomain inhibitors (JQ1) preventing MYC transcription decreased cell viability in vitro and tumor growth in vivo." (PMID 29463565, 2018). "We identified MYC as a key master regulator of proliferation activated by aberrantly activated FGFR3 in bladder cancer‐derived cell lines." (PMID 29463565, 2018). "In summary, knockdown of MYC by synthetic regulatory RNAs can inhibit bladder cancer cell growth in vivo." (PMID 29084575, 2017). "High expression of MYC was significantly correlated with bladder cancer histological grade and TNM stage." (PMID 29084575, 2017). "In our study, we constructed synthetic artificial miRNA devices driven by UAS to suppress the expression of the MYC oncogene in bladder cancer." (PMID 29084575, 2017). "High expression of MYC was significantly correlated with bladder cancer histological grade (P = 0.031) and TNM stage (P = 0.016)." (PMID 29084575, 2017). "In short, synthetic regulatory RNAs selectively inhibit the progression of bladder cancer through controlling the expression of amiRNAs targeting MYC." (PMID 29084575, 2017).
bladder cancer (continued). "To investigate the function of this gene in bladder cancer cells, we synthesized specific siRNA duplexes to knockdown MYC expression." (PMID 29084575, 2017). "In bladder cancer, increase of MYC copy number occurred before muscle invasion and correlated with grade." (PMID 29084575, 2017). "As a famous oncogene in other cancer, PVT1 is located in chromosome 8q24 and is closely near MYC which promotes progression of bladder cancer." (PMID 26517688, 2015). "We also analyzed the diagnostic accuracy of DNA integrity of three oncogenes (c-MYC, HER2, and BCAS1) which are known to be involved in the development of bladder cancer." (PMID 23509700, 2013). "Given that frequent MYC over-expression or amplification has been described in bladder cancer, MYC seems to play an important role in bladder cancer development." (PMID 23752272, 2013). "POLD1 stabilizes MYC and leads to faster cell growth and metastasis in bladder cancer cells." (PMID 39910288, 2025). "Moreover, genes such as NAT2, TP63, GSTM1, MYC, TACC3‐FGFR3, PSCA, CLPTM1L‐TERT, APOBEC3A‐CBX6, UGT1A, and CCNE1 get mutated in bladder cancer." (PMID 40755497, 2025). "Furthermore, our investigations revealed an intricate interaction between YARS1 and MYC in the regulation of bladder cancer cell senescence, ferroptosis and stemness." (PMID 38506098, 2024). "MYC is a key downstream effector of activated FGFR3 that mediates tumorigenesis in bladder cancer." (PMID 39031286, 2024). "MYC also regulates expression of GClnc1, a long non-coding RNA (lncRNA) that significantly promotes J82 and 5637 bladder cancer cell invasion and metastasis by elevating MYC activity, consistent with reports that GClnc1 overexpression in bladder cancer can promote cell migration and invasiveness." (PMID 37450923, 2024). "However, MYC knockdown in bladder cancer cells led to significant resistance to A80.2HCl effects, indicating that the inhibitory effect of A80.2HCl likely depended on MYC expression." (PMID 38424044, 2024). "Several proteins and RNAs that directly or indirectly interact with MYC affecting its expression and protein stability may also play roles in the pathogenesis of bladder cancer." (PMID 39031286, 2024). "MYC overexpression is commonly observed in many human cancers including bladder cancer." (PMID 39031286, 2024). "Moreover, data from mouse tumors and human bladder cancer tissues confirmed the repression of pRB1 protein abundance mediated by MYC and KLHL42." (PMID 38424044, 2024). "Ubiquitin C-terminal hydrolase-L5 (UCHL5), a member of the DUBs family of proteins that is overexpressed in bladder cancer, has been indicated to promote the growth and migration of bladder cancer cells by increasing MYC expression through the AKT/mTOR signaling pathway." (PMID 39031286, 2024). "Furthermore, our previous study has confirmed that MYC regulates senescence in bladder cancer cells." (PMID 38506098, 2024). "Based on these findings, we hypothesized that YARS1 interacts with MYC to regulate bladder cancer cell senescence, ferroptosis and stemness." (PMID 38506098, 2024). "Finally, we established a ceRNA network that is directly linked to the overall prognosis, YARS1 can serve as a prognostic biomarker for bladder cancer; its interaction with MYC has implications for bladder cancer cell senescence, ferroptosis and stemness." (PMID 38506098, 2024). "Interestingly, the mechanism by which METTL3 enhances MYC expression in an m6A-dependent manner to regulate tumor growth also exists in cervical cancer, bladder cancer, acute myeloid leukaemia, and oral squamous carcinoma." (PMID 37996892, 2023). "In bladder cancer, the expression of MYC is activated by AKT-mTOR signaling." (PMID 37173935, 2023). "Recently, Wu revealed BRD4 as a novel promising target for pharmacologic treatment against bladder cancer and reported that BRD4 regulates proliferation and apoptosis of bladder cancer cells by positively regulating EZH2 transcription through upregulation of c-MYC." (PMID 36733715, 2023).